CTNNB1 (catenin beta 1)
Diseases named in the same sentence as CTNNB1 in open-access papers (continued):
Sharing a sentence is not in itself a finding about the gene and the disease.
cancer (continued). "CTNNB1 pathogenic variants are related to the improper functioning of the WNT/β-catenin pathway, promoting the development of different types of cancer of somatic origin." (PMID 39202333, 2024). "The distribution patterns of several known cancer driver genes, including CTNNB1, ATM, CHEK2, and NCOR1, exhibit racial disparities across datasets." (PMID 39541191, 2024). "In contrast, the enrichment of H3K4me3 at CTNNB1’s promoter was comparable between cancer and native tissues." (PMID 39320349, 2024). "In summary, we identified overexpression of CD24, CTNNB1, and SOX4 signatures in CRC, revealing their association in promoting tumorigenic properties, cancer stemness, and resistance to therapy." (PMID 38203779, 2024). "Various signaling pathways such as Wnt, Notch, and Ephrin signaling pathways have been needed to reveal the CTNNB1 signaling in cancer." (PMID 38612999, 2024). "The catenin beta 1 gene (CTNNB1) plays a crucial role in the malignant progression of various cancers." (PMID 37740194, 2023). "We further investigated the effects of the interplay and the underlying mechanisms between circ‐CTNNB1 and RBM15 on the regulation of target genes (GPI, HK2 and PGK1) and cancer progression in OS cells." (PMID 36181462, 2023). "Local delivery of anti–TNF-α neutralizing antibody rescues the pro-metastatic effects of β-catenin activation in AMs, and TNF correlates with CTNNB1 expression in the AMs of cancer patients." (PMID 37092550, 2023). "Together, these studies suggest that both BCL9/9l and Pygo1/2 are attractive therapeutic targets in cancers that harbour mutations in both APC and CTNNB1." (PMID 37048063, 2023). "MYC overexpression has been noted in addition to CTNNB1 in cancer stem cells, as it is a transcription factor that controls cell growth, differentiation, and cell maintenance." (PMID 37370820, 2023). "Next, an upset Venn diagram was used to identify the overlapping genes among the KEGG pathways related to the EMT process, the Wnt/β−catenin pathway, and cancer; CTNNB1, also known as β−catenin, was the intersection gene of each pathway." (PMID 36982956, 2023). "Genomic profiles of cancer patients identified that tumor-induced mutations in KRAS, STK11, KEAP1, CDKN2B, CTNNB1, and MET are significantly associated with cancer-associated thrombosis." (PMID 37046748, 2023). "Our previous study demonstrated the essential roles of the circ‐CTNNB1/DDX3/YY1 axis in cancer progression." (PMID 36181462, 2023). "In the present study, we observed the colocalization of RBM3 protein with the mRNA of CTNNB1 when cancer cells were co-cultured with osteoblast cells to mimic a bone microenvironment." (PMID 36750551, 2023). "In a previous study, we identified that circ‐CTNNB1 drives cancer growth, invasion, and metastasis through the activation of β‐catenin in cancer, while no further studies have been conducted on this circRNA in OS." (PMID 36181462, 2023). "Mutations in STK11, CDKN2B, KEAP1, CTNNB1, MET, and KRAS were associated with a significantly increased risk of cancer-associated thrombosis." (PMID 38069251, 2023). "The most prevalent altered cancer-related genes were CTNNB1 (16%) and ZNRF3 (16%), followed by EGFR (11%), JARID2 (11%), KMT2B (11%), KMT2C (11%), NSD1 (11%), PIK3CA (11%), SH2B3 (11%), and UBR5 (11%)." (PMID 38023213, 2023).
cancer (continued). "We observed that 28.6% (2/7) of CTNNB1 wild-type patients died of cancer, contrasting with CTNNB1 mutant cases, where any patient died of cancer (p=0.01)." (PMID 37746264, 2023). "In contrast to these studies, our data suggested that the most prevalent altered cancer-related genes were CTNNB1 (16%) and ZNRF3 (16%)." (PMID 38023213, 2023). "Recent studies have revealed the pivotal functions of circ‐CTNNB1 (a circular RNA derived from CTNNB1) in cancer progression." (PMID 36181462, 2023). "Our results revealed that the molecule MCULE-2386589557-0-6 interacts with AJUBA, leading to a misplaced interaction between AJUBA and CTNNB1, interfering in this pathway and probably preventing its role in cancer establishment." (PMID 37765273, 2023). "Of these genes, GNAQ, GNAS, and JAK2 are associated with cell growth-related factors, whereas NRAS, IDH2, and CTNNB1 are cancer-related genes." (PMID 36780540, 2023). "Inconsistent with our result, a previous study detected overexpression of WNT and CTNNB1 in CRC tissues compared with para-carcinoma tissues." (PMID 37644520, 2023). "It is of interest to note that GBA organoids already have mutations in some cancer‐related genes (e.g., CTNNA2 and CTNNB1), suggesting the malignancy potential of some GBA cells." (PMID 35075805, 2022). "The upregulation of CTNNB1 as an epithelial-mesenchymal transition (EMT)-related gene has a significant role in the regulation of cancer signaling." (PMID 35041720, 2022). "Through a comprehensive analysis of cancer genomes based on deep sequencing, it became evident that mutations in APC, CTNNB1, and Axin are frequently detected in many types of human cancers, such as colorectal and liver cancers, with β-catenin accumulation." (PMID 35053606, 2022). "In all the four components, two pathogenic mutations, known to be recurrent hotspots in cancer, were present: PIK3CA c.3140A > T p.(His 1047Leu) and CTNNB1 c.94G > T p.(Asp32Tyr)." (PMID 34342838, 2022). "For instance, a recent study revealed that the transcription of CTNNB1 in cancer cells was mediated by MEF2A, which can be occupied by KMT2D." (PMID 35477537, 2022). "The causality of the CTNNB1 mutation and hepatocarcinogenesis thus confers AKT2/CAD signaling cascade-mediated pyrimidine synthesis a druggable vulnerability for CTNNB1 mutant cancer." (PMID 36122209, 2022). "We found that ECs harbored not only known mutations in driver genes, such as ARID1A, CTNNB1, PIK3CA, and PTEN, but also novel mutations in cancer-related genes, such as KMT2C and PRKAR1A." (PMID 35626111, 2022). "Differences in survival and recurrence between CTNNB1 mutant and wild-type EECs are typically observed in low grade cancers only." (PMID 36248967, 2022). "ELF3, which is predicted to drive the expression of highly expressed ID genes ANXA3, TGFB2, and duct marker KRT8, has been shown to drive ligand-independent transactivation of CTNNB1 in cancer models." (PMID 36540608, 2022). "For example, TGFB upregulation, CTNNB1 activation, and loss of PTEN and JAK2 reduce T cell priming and infiltration in cancer, leading to immune escape and immunotherapy resistance." (PMID 36119104, 2022). "Mutations in cancer-related genes (KMT2C, NOTCH2, PRKAR1A, SDHA, and USP6) and genes related to EC (ARID1A, CTNNB1, PIK3CA, and PTEN) were identified with high frequencies among the three samples." (PMID 35626111, 2022).
cancer (continued). "Further, more than 80% of cancer patients have methylation of SOX17 promoter, which is negatively associated with the accumulation of nuclear CTNNB1." (PMID 36457029, 2022). "Depending on the stage and type of cancer, the Wnt-CTNNB1 signaling pathway can either promote or inhibit tumor initiation, growth, metastasis, and drug resistance." (PMID 36142412, 2022). "In summary, we revealed that DPP4, CTNNB1, and MET oncogenic signatures are overexpressed in THCA, and are associated with cancer progression, metastasis, resistance, poor disease-free survival, and unfavorable clinical outcomes." (PMID 35205190, 2022). "We decided to focus on CTNNB1 and MUC16, which are recognized as being associated with cancer, for a further investigation." (PMID 36199046, 2022). "CTNNB1 had the highest mutation rate (29%), and the CNV was markedly positively correlated with CTNNB1 expression in human cancers." (PMID 35274003, 2022). "All the significant nine representative terms covered 16 genes with 6 NCG cancer genes CTNNB1, PML, RB1, MLL2, ARNT and NRIP1 belonging to at least three representative terms." (PMID 34504716, 2021). "The AKT/GSK3β/CTNNB1 signaling pathway is critical for the progression of several cancers, including HCC." (PMID 34950583, 2021). "EDN1, CEBPD, and CTNNB1 are key players in triggering cancer-promoting pathways, including EMT and Wnt/β-catenin signaling pathways." (PMID 34680563, 2021). "The core component genes of the pathway CTNNB1, encoding for β catenin, APC and CDH1, encoding for E cadherin, are less frequently mutated, but also their prevalence is higher in PIK3CA mutated cancers than wild-type ones." (PMID 33435133, 2021). "Overall, 34 specimens harbored driver mutations in five cancer genes (EGFR, PIK3CA, KRAS, CTNNB1, and MET), which are canonical driver mutations." (PMID 33407425, 2021). "Higher mutated frequency in Wnt signalling of pancreatic body/tail cancers mainly resulted from distinctly enriched SMAD4 mutations (P = 0.008), and more abundant LRP1/1B and CTNNB1 mutations." (PMID 33452856, 2021). "In addition, as somatic MLH1 and CTNNB1 mutations seem to be non-independent events, large deletions of the MLH1 gene prevailing in the Finnish population as a founder variant may have an impact on the routes of cancer progression and the likelihood of somatic CTNNB1 mutations." (PMID 34206061, 2021). "By analyzing the mRNA abundance of CIRP and CTNNB1, we found that CIRP and CTNNB1 were positively correlated in these cancer samples." (PMID 34465343, 2021). "WNT3A regulates cancer cell stemness and increases metastatic potential via CTNNB1 signaling pathway and upregulation of Notch3 31,32." (PMID 34093821, 2021). "The NGS analyses identified mutations in eight cancer associated genes: ESR1, MECOM, JAK3, KMT2C, CTNNB1, CALR, NCOR1 and AMER." (PMID 34209696, 2021).
cancer (continued). "Of note, positive correlations of ASPH with GSK3B and CTNNB1 have been found in the normal tissues, cancer tissues as well as cancer cell lines." (PMID 33015050, 2020). "Apart from the most frequent mutations of APC in colorectal cancer and CTNNB1 in hepatocellular carcinoma, deregulations of several extracellular modulators of WNT-signaling e.g., DKKs, sFRPs and WIF1 also contribute to cancer development." (PMID 32659938, 2020). "While NGS analysis unveiled common mutations in PTEN, CTNNB1, and ARID1A, different PIK3CA and PIK3R1 mutations were also detected, suggesting the existence of at least two cancer clones." (PMID 32652986, 2020). "While CTNNB1 alterations have been investigated extensively in human cancers, only a few studies have drawn attention to biallelic mutations." (PMID 33115416, 2020). "Taking all these data into account, we identified the following candidates as potential causes of CA in human cancer: gain of function of CEP19, CEP72, CTNNB1, PTK2, NDRG1, SPATC1, TBCCD1; and loss of function of CEP76, MCPH1, NEURL4, NPM1." (PMID 32681070, 2020). "The WNT/CTNNB1 pathway plays an important role in multiple developmental processes and stemness and is upregulated in many other cancer types." (PMID 32366847, 2020). "To analyze the relationship between malignant tumor proliferation level and CTNNB1: rs1880481, we collected data on the ki67 proliferation index in 105 NSCLC patients with bone metastasis." (PMID 32453708, 2020). "As expected for a Wnt-addicted cancer, all 5 sgRNAs targeting CTNNB1 were also depleted in both in vitro and in vivo screens." (PMID 33092630, 2020). "To achieve this, we transduced the stabilized version of Ctnnb1 downstream of APC, because Apc requires biallelic mutations for cancer initiating Wnt activation which seem to (inter)depend on the intestinal location." (PMID 33292279, 2020). "CTNNB1 is part of a complex of proteins that constitute adherens junctions, which is correlated with cancer pathogenesis." (PMID 33363164, 2020). "This list of commonly mutated cancer genes contained 3 centrosome genes: CEP76, CTNNB1, and NPM1, which were included in our analysis." (PMID 32681070, 2020). "Additional hits, perhaps in a particular order, in other cancer drivers, such as in the oncogene Catenin beta-1, and in the promoter region of telomerase reverse transcriptase are probably required to confer differential selective advantages." (PMID 32942546, 2020). "Nevertheless, except from CTNNB1, Varns comprised in the Cancer Gene Census appeared rather infrequently among the examined HCCs." (PMID 31039795, 2019). "We analyzed 160 cancer-related genes for mutations in just 2 days using NGS and detected only one mutation in the CTNNB1 gene." (PMID 30206803, 2019). "In particular, genes like MYC, MKI67, CTNNB1, PCNA, NKX3.1, ACPP and kallikreins are warranted further investigation as diagnostic markers for cancer and cell proliferation." (PMID 31519932, 2019). "The poor survival samples also over-expressed CTNNB1 and SOX4 and under-expressed PIK3R1 and TP63, all of which have been linked to tumorigenesis in other cancers." (PMID 29484115, 2018). "Many gene mutations of the canonical WNT/β-catenin pathway giving rise to cancers have been reported (CTNNB1, AXIN, APC)." (PMID 29706964, 2018).
cancer (continued). "As CTNNB1 was the truncal gene in ACC, we explored compounds in GDSC database with significant selectivity to cancer cells harboring CTNNB1 mutation." (PMID 29532999, 2018). "Two upstream regulators identified in our prognostic study, TCF1 and CTNNB1, emphasized the potential role of Wnt signaling pathway whose improper activation is responsible for establishment of cancer stem cells." (PMID 29515771, 2018). "A second set consisted of an additional 15 cancer-related genes (Nf1, Mki67, Mllt4, Fgfr2, Ctnnb1, Fat1, Clp1, Fat4, Arid1a, Nat1, Nat2, Setd2, Impg1, Nbas and Npat)." (PMID 29925311, 2018). "Two control mRNAs, CTNNB1 (β-catenin) and hTERT, which are constitutively expressed in cancer cells, were unaffected, suggesting that the effect on SOX4 mediated by iEVs-335 was specific." (PMID 30514916, 2018). "Frequent somatic alterations in CTNNB1, gene that encodes β-catenin, or components of its regulatory network, such as APC and AXIN, have been detected in human cancers." (PMID 29383099, 2017). "These DMS were mapped to genes including Fgf3, Ctnnb1 and Pkm, known to be involved in cancer-related pathways." (PMID 29073177, 2017). "When applied on 40 ng of DNA from fresh HCT116 cells, eight variants were detected, including KRAS (p.G13D), PIK3CA (p.H1047R), and CTNNB1 (p.S45del), with all of them being reported in ATCC or in COSMIC (Catalog of Somatic Mutations In Cancer)." (PMID 29263843, 2017). "A total of 409 genes from the Ampliseq Comprehensive Cancer Panel (Ion Torrent, Thermo Fisher) were analysed by next generation sequencing and mutations in 10 genes, including ARID1A, CTNNB1, PIK3CA and PTEN were identified and confirmed by Sanger sequencing." (PMID 28103826, 2017). "Across all anatomic sites, 4% of carcinomas had at least one CDH1 mutation and 4% of carcinomas had at least one CTNNB1 mutation." (PMID 29156750, 2017). "We also measured the expression of CTNNB1 (β-catenin) mRNA, which is frequently overexpressed in various cancer patient tissues." (PMID 26415221, 2015). "The altered splicing event in CTNNB1 in U2AF1 mutant cancers results in a shift toward splicing of a more proximal splice site in the 3′ UTR of CTNNB1." (PMID 24498085, 2014). "The second subgraph, which contains the largest number of component nodes, has its 95 nodes anchored to the known cancer proteins CTNNB1, APC, PTEN, TP63, MAPK4, MET, RAC1, and ROS1." (PMID 24516372, 2014). "Clinical treatment of CTNNB1-mutant cancers with MEK inhibitors is therefore worth further investigation." (PMID 24651269, 2014). "Imbalance in the structural and signaling properties of CTNNB1 often results in deregulated growth connected to cancer and metastasis." (PMID 23405266, 2013). "ActiveDriver identifies N-terminal mutations in five cancer types as highly significant (n = 73, FDR p = 2.5e − 92 from ActiveDriver), confirming constitutive activation of CTNNB1 via disrupted phosphorylation as a prevalent driving mechanism of cancer." (PMID 24089029, 2013). "In cancer, mutations in APC or CTNNB1 (β-catenin) lead to permissive β-catenin machinery, subverting TCF/LEF transcription factors to unleash tumorigenic gene expression, including MYC, CCND1, and AXIN2, promoting unbridled proliferation, stemness, and therapeutic resistance." (PMID 40874062, 2025).